IL6 (interleukin 6)
Diseases named in the same sentence as IL6 in open-access papers (continued):
Sharing a sentence is not in itself a finding about the gene and the disease.
cardiovascular disease (continued). "The levels of plasma interleukin 6 and its soluble receptors were found to be elevated in subjects with cardiovascular diseases, which points to amplification of the IL-6-mediated trans-signaling pathway in cells and the development of chronic inflammation." (PMID 33659786, 2020). "Cardiovascular diseases were more prevalent in the elevated IL-6 group (44.17%) than in the normal IL-6 group (20.23%); similarly, neurological diseases were also more common in the elevated IL-6 than in the normal IL-6 group (11.76 vs. 4.93%)." (PMID 32765283, 2020). "IL-6 also stimulates the production of C-reactive protein (CRP), which is a marker for the evaluation of systemic inflammation and risk of developing cardiovascular diseases." (PMID 31394805, 2019). "Several studies have shown that IL-6 and IL-8 are important mediators of inflammation and contribute to the development of cardiovascular diseases." (PMID 30723500, 2019). "Recent evidence has revealed that inflammation is a critical pathological process of CHF and high levels of IL-6, a proinflammatory cytokine, have been reported to be an important mediator in chronic inflammatory and cardiovascular disorders." (PMID 31619994, 2019). "In patients with cardiovascular diseases, β-carotene was significantly correlated with IL-6 and CRP." (PMID 30991720, 2019). "Cardiovascular diseases (CVD) are group of complex and multifactorial pathologies, in which interleukin-6 (IL-6) gene polymorphisms have been associated with several components of the CVD." (PMID 31338006, 2019). "During the initial steps, the progression of cardiovascular disorders can be influenced by inflammatory reactions, whereby cytokines such as interleukin 6 (IL-6) and TNF-α are induced." (PMID 31394805, 2019). "As previously discussed, IL-1 is an attractive drug target for inflammation in cardiovascular disease due to its direct role in transducing inflammasome activation as well as its position upstream of not only IL-6 but multiple other inflammatory mediators." (PMID 30873416, 2019). "Men had significantly lower age and higher levels in the GSI, higher BMI, IL-6 and more cardiovascular disease as well as higher Trp and lower Kyn/Trp compared to females." (PMID 30846946, 2019). "Nonetheless, there are ongoing discussions regarding future trials of IL-6 inhibitors in cardiovascular disease." (PMID 30873416, 2019). "It is well known that inflammatory mediators, especially IL-6, are central to the development of cardiovascular diseases." (PMID 31338006, 2019). "For instance, the clinical quantification of IL-6 is a strong predictor for mortality in pancreatic and cardiovascular disease." (PMID 31795299, 2019). "In this sense, %BF below the health risk value helps to control low-grade inflammation in the arterial wall, that is, it contributes to avoid the inflammatory action of CRP and IL-6, whose non action consequently helps avoiding cardiovascular diseases." (PMID 30624536, 2019). "Clinical studies suggest that suPAR has an additive value to high-sensitivity C-reactive protein (hsCRP) or interleukin-6 (IL-6) in characterizing systemic inflammation in cardiovascular diseases." (PMID 30820636, 2019). "Consumption of bilberry juice by patients with an increased risk for cardiovascular disease led to decreased plasma concentrations of CRP, IL-6 and IL-15." (PMID 30307962, 2018). "For instance, IL-6 is a known downstream target of IL-1β, consistently increased in patients with NLRP3 inflammasome-mediated conditions, such as cardiovascular disease and associated with clinical outcomes." (PMID 30483114, 2018). "The actions of IL-6, such as inflammation induction, fibrinogen concentration elevation, an increase in platelets and coagulation promotion, support the role of IL-6 in the development of cardiovascular disease." (PMID 30423923, 2018). "Clinically, increases in plasma IL-6 and TNF-α have been associated with cardiovascular disease and disease outcomes." (PMID 29157250, 2017).
cardiovascular disease (continued). "Development of new treatments (e.g., sgp130fc) aiming at specific inhibition of IL-6 trans-signaling seems to be a promising avenue also for the treatment and prevention of cardiovascular disease." (PMID 28250574, 2017). "Markers of inflammation, in particular C-reactive protein (CRP) and interleukin 6 (IL-6), have been reported as predictors of cardiovascular diseases." (PMID 28865434, 2017). "Interleukin-6 (IL-6) is one of the most important cytokines and is widely used in the cardiovascular laboratories for cardiovascular disease evaluation." (PMID 29186872, 2017). "IP10, IL6 and hs-CRP have been demonstrated to be risk factors for metabolic and cardiovascular diseases." (PMID 28060925, 2017). "One of the primary effects of IL-6 is to induce the production of hepatic CRP, which is a known independent risk factor of cardiovascular disease." (PMID 28555043, 2017). "The pro-inflammatory cytokine IL-6 plays an important role in cell proliferation and is involved in the processes of many cardiovascular diseases." (PMID 27412561, 2016). "The data presented above illustrate that IL-6 is a key mediator, which is linked to T2DM and cardiovascular diseases in women with PCOS." (PMID 26849353, 2016). "Patients with higher NTproBNP and cTnI were older, more likely to have a history of cardiovascular disease, and have elevated IL-6 levels." (PMID 26897129, 2016). "In conclusion, symbiotic supplementation can reduce serum hs-CRP, IL-6 and TNF-α concentrations, a risk factor for cardiovascular diseases." (PMID 26153197, 2015). "A previous study found that the mortality rate of individuals with cardiovascular diseases in a five-year follow-up period was able to be predicted based on the elevated concentration of IL-6 in the peripheral blood." (PMID 25574216, 2015). "IL-6, an intense inflammatory cytokine, plays a critical role in cardiovascular disease, and it can activate endothelial cells and regulate the extracellular lipids." (PMID 26539229, 2015). "Symbiotic supplementation can reduce serum hs-CRP, IL-6 and TNF-α concentrations, a risk factor for cardiovascular diseases." (PMID 26153197, 2015). "Inflammatory cytokine IL-6 is secreted by macrophages and T cells as a response to inflammation and is considered as one of the crucial cytokines regarding cardiovascular disease." (PMID 25861161, 2015). "This research on IL-6 is shedding further light on the pathogenesis of PCOS and the long-term cardiovascular disease risk associated with PCOS." (PMID 25096410, 2014). "Conversely, there were no significant changes from baseline to Week 24 in any of the biomarkers associated cardiovascular disease, inflammation or thrombogenesis that were evaluated (hs-CRP, interleukin-6 and D-dimer) either within or between treatment groups." (PMID 24825167, 2014). "Chronic stress has also been shown to induce a chronic and systemic state of mild inflammation (i.e., C-reactive protein and interleukin-6) a key mechanism in the development of cardiovascular disease." (PMID 25374338, 2014). "Multiple cardiovascular disorders are associated with increased levels of circulating pro-inflammatory cytokines, especially TNF-α and IL-6, which are related to a common cytokine profile found in acute and chronic HF patients independently of etiology." (PMID 25303100, 2014). "Levels of the inflammatory marker IL-6 are also higher in patients with COPD with cardiovascular disease and frequent exacerbators have higher levels of IL-6 and fibrinogen than infrequent exacerbators." (PMID 23945277, 2013). "IL-6 is produced in response to inflammation and has been implicated in the progression to ALI and cardiovascular disease." (PMID 23691180, 2013). "Among kidney disease patients serological biomarkers related to cardiovascular disease (fibrinogen, interleukin 6, C-reactive protein) were measured." (PMID 23294625, 2013).
cardiovascular disease (continued). "Four variables age (P = 0.008), serum IL-6 (P = 0.008), serum hs-CRP (P < 0.0001), and the -174G>C polymorphism (P = 0.029) were significantly associated with cardiovascular disease phenotype." (PMID 24363620, 2013). "Elevated levels of monocyte chemoattractant protein (MCP-1), interleukin 6 (IL6), and tumor necrosis factor alpha (TNFα), produced by the immune system play important roles in increasing the risk of cardiovascular disease." (PMID 22883023, 2012). "The relevance of these results is emphasized by the fact that IL-6 plays a central role in the inflammatory response in the context of cardiovascular disease." (PMID 22769230, 2012). "The proinflammatory cytokines such as tumor necrosis factor alpha and interleukin-6, involved in the pathogenesis of RA, are also independently predictive of subsequent cardiovascular disease (CVD)." (PMID 23024462, 2012). "Finally, the results obtained suggest that high IL-6 in young PCOS subjects may also represent a signal of altered immune response that may enhance the identification of subjects featuring an increased risk of cardiovascular disease later in life." (PMID 21547256, 2011). "Systemic production of IL-6 could induce the acute phase response in liver, which entails the production of pro-coagulant factors such as plasminogen activator inhibitor 1 and antimicrobials such as C-reactive protein, whose increased concentrations have been associated with cardiovascular disease." (PMID 21054880, 2010). "Moreover, the results strongly suggest that further elevation of certain inflammatory markers, such as CRP, IL-6, and sVCAM-1, could be considered as markers of severity of cardiovascular disease and consequently higher risk of developing a cardiovascular event in dyslipidemic subjects." (PMID 19584917, 2009). "Although IL-6 is clinically considered to be a biomarker of cardiovascular disease, emerging evidence indicates that IL-6 signaling plays a central, significant biological role in cardiovascular regulation." (PMID 19936194, 2008). "In summary, IL-6 is a major indicator of significant cardiovascular disease of diverse etiologies and has emerged as a multi-faceted regulator of vascular tone and cellular inflammation." (PMID 19936194, 2008). "Furthermore, inflammation is a link between aging and cardiovascular disease, as aging presents with systemic low-grade chronic inflammation and elevated concentrations of mediators such as IL-6, TNFα, and C-reactive protein (CRP)." (PMID 40869066, 2025). "IL-6 plays a dual role by indirectly stimulating central nervous system inflammation through the blood–brain barrier and influencing cognition through its effect on cardiovascular disease." (PMID 40950978, 2025). "While preliminary studies suggest that IL-6 inhibition may play a role in cardiovascular diseases, its specific effects in HF remain to be fully established." (PMID 40002874, 2025). "Risk-based screening protocols for cardiovascular disease and metabolic dysfunction should be considered in this population, potentially guided by inflammatory and endothelial biomarkers (e.g., hs-CRP, sVCAM-1, IL-6)." (PMID 41007819, 2025). "The release of these fatty acids, coupled with some inflammatory cytokines production like tumor necrosis factor-alpha (TNF-α) and interleukin-6 (IL-6), instigates systemic inflammation and the onset of metabolic disorders like cardiovascular disease and type 2 diabetes." (PMID 39774749, 2025). "MIAT is closely related to cardiovascular disease and is involved in the NF-κB pathway, promoting the expression of pro-inflammatory cytokines like IL-6 and TNF-α, and influencing the osteogenic differentiation of human adipose-derived and bone marrow mesenchymal stem cells." (PMID 39898106, 2025). "However, patients with high IL-6 concentrations had higher preoperative concentrations of cardiac biomarkers, suggesting the presence of subclinical cardiovascular disease." (PMID 40491666, 2025).
cardiovascular disease (continued). "Colitis inflammation, in part mediated by IL-6, has been associated with platelet hyper-responsiveness and an increase in circulating platelet–leukocyte aggregates (PLA) and activated platelets, possibly contributing to cardiovascular disease." (PMID 40497942, 2025). "In this regard, several clinical trials are currently evaluating immunomodulatory strategies in cardiovascular disease, including IL-6 blockade with ziltivekimab, selective NLRP3 inhibitors such as dapansutrile, and established anti-inflammatory agents such as colchicine and canakinumab." (PMID 40943136, 2025). "However, few trials have specifically assessed the efficacy of drugs targeting the IL-6 pathway in the acute setting of cardiovascular disease, providing early signals supporting its feasibility, thus offering a rationale for further investigation in CS." (PMID 40884675, 2025). "Elevation of IL-6 is a key factor in the incidence of cardiovascular diseases in RA patients." (PMID 40305360, 2025). "There are also established connections between IL-6 and cardiovascular disease." (PMID 40700294, 2025). "In fact, previous research has confirmed that EAT participates in the occurrence and progression of cardiovascular diseases by synthesizing and secreting proinflammatory mediators and neurohormones such as IL-1β, IL-6, TNF-α, MCP-1, resistin, visfatin, and others." (PMID 38277087, 2024). "Increased levels of IL-6 have been associated with negative outcomes in individuals, both with and without pre-existing cardiovascular disease (CVD)." (PMID 39519510, 2024). "Moore and colleagues (2013) examined whether a brief Behavioral Activation intervention would reduce biomarkers of cardiovascular disease, including IL-6 and D-dimer." (PMID 38300637, 2024). "In addition, interleukin (IL) 1β, IL-6, or tumor necrosis factor (TNF) are reported to affect cardiovascular disease by circulating throughout the body and causing responses in other tissues." (PMID 39093905, 2024). "Elevated interleukin (IL)-6 levels have been linked to adverse outcomes in patients with and without baseline cardiovascular disease (CVD)." (PMID 39077632, 2024). "At the same time, another meta-analysis of randomized clinical trials aimed to determine the effect of statins on serum levels of TNF-α, MCP-1, VCAM1 and IL-6 in patients with cardiovascular diseases showed that statins have a beneficial effect on reducing the serum levels of TNF-α." (PMID 38572445, 2024). "It has been suggested that IL-6 may play an important role in the disease activity of SS, as well as the secondary tumorigenesis and cardiovascular disease." (PMID 38728503, 2024). "Apart from IL-6 and IL-1β, other inflammatory markers may also play critical roles in cardiovascular diseases." (PMID 39057626, 2024). "TNF-α and IL-6 are key inflammatory factors in cardiovascular diseases." (PMID 39275259, 2024). "Similarly, the pathogenesis of metabolic and cardiovascular diseases is intimately linked with the activity of proinflammatory cytokines such as tumor necrosis factor-alpha (TNF-α) and interleukin-6 (IL-6)." (PMID 38398830, 2024). "The detection of inflammatory biomarkers, such as CRP or IL-6 adhesion molecules, may be a good way of diagnosing atherosclerosis and cardiovascular disease." (PMID 37509542, 2023). "Our recent work demonstrated that Cad-11 participates in obesity-induced atrial fibrosis and susceptibility to atrial fibrillation by regulating the secretion of inflammatory factors IL-6 in atrial fibroblasts, implicating a role of Cad-11 in cardiovascular diseases." (PMID 37047522, 2023). "For this reason, the fact that there is a relationship between IL-6 and cardiovascular disease in our work could be mediated by the interrelation between both IL-6 and CRP." (PMID 37762312, 2023).
cardiovascular disease (continued). "The associations were attenuated but many remained statistically significant in the full sample (IL‐6, IL‐7, IL‐8, LIF‐R, and LAP TGF‐beta‐1) after adjustment for cardiovascular disease and risk factors, suggesting additional biologic pathways play a role in these associations." (PMID 37584418, 2023). "Indeed, a clinical study in which anti-IL-6 drugs were administered for the purpose of treating cardiovascular disease demonstrated that biomarkers of inflammation and thrombosis were decreased in CKD patients." (PMID 37176037, 2023). "Statins have been shown to reduce the levels of hs-CRP and IL-6 in patients with cardiovascular disease, suggesting that they may help to reduce inflammation and lower cardiovascular risk." (PMID 37048603, 2023). "Our study emphasizes the importance that IL-6 could have in cardiovascular disease and complement system disruption of SLE patients." (PMID 37762312, 2023). "Nevertheless, there is preliminary evidence suggesting a possible association between positive psychological processes (e.g., positive affect, gratitude) and lower levels of inflammatory markers (e.g., TNF-α, interleukin-6, C-reactive protein) in individuals with cardiovascular disease." (PMID 37213708, 2023). "The NLRP3-inflammasome and the interleukin 6 (IL-6)-pathways are central in cardiovascular disease." (PMID 36140297, 2022). "Moreover, elevated serum levels of TNF-α, IL-6 and CRP have been shown to increase the risk of cardiovascular diseases." (PMID 36434695, 2022). "We also confirmed our hypothesis that overeating behavior was prospectively associated with higher systemic inflammation as reflected by IL-6, which has been of clinical interest in predicting cardiovascular disease." (PMID 36100924, 2022). "Elevated IL-6 levels are related to higher mortality rate in people with cardiovascular diseases." (PMID 35887619, 2022). "However, significantly higher levels of IL6 are observed in people who develop cardiovascular disease (CVD)." (PMID 35566778, 2022). "As the activation of inflammatory pathway is a crucial pathological event in the occurrence and development of HF, and IL-6 is one of the most well-characterized and principal cytokines in cardiovascular disease, understanding the specific role of IL-6 in HF counts for the target therapy in HF." (PMID 34504432, 2021). "Evidence indicates that the effect of EAT on cardiovascular disease may mainly result from its release of endocrine proinflammatory mediators such as interleukin-6 (IL-6) and TNF-α." (PMID 33978815, 2021). "Hence, there is reason to believe that inhibitors of IL-6 have a protective effect against Cardiovascular Diseases." (PMID 34504432, 2021). "Furthermore, IL-6 and IL-1β are both involved in a broad range of other biological activities, regenerative processes, metabolic control, and the prevention of cardiovascular disease." (PMID 34945535, 2021). "On the other hand, IL-6 and its soluble receptor sIL-6R form a complex of the IL-6 trans-signaling pathway that is related to pathological responses such as tissue fibrosis, inflammatory arthritis, and cardiovascular disease." (PMID 34434114, 2021). "Indeed, our recent single-cell RNA-sequencing study revealed that monocytes of patients with cardiovascular disease carrying CHIP driver mutations are primed for exuberant inflammatory responses and IL-6 production." (PMID 33211155, 2021). "It has been evident that many factors such as oxidized low-density lipoprotein (ox-LDL), angiotensin II (Ang II), and interleukin-6 (IL-6) can impair the barrier and secretion functions of VECs in different cardiovascular diseases, leading to an acceleration of disease progression." (PMID 34327240, 2021). "It has been reported that simvastatin inhibits IL-6, IL-8 and IL-1β production in vitro, which may contribute to its protective role in cardiovascular diseases." (PMID 33327440, 2020).